SIRT1 (sirtuin 1)
Diseases named in the same sentence as SIRT1 in open-access papers (continued):
Sharing a sentence is not in itself a finding about the gene and the disease.
Hyperglycemia (continued). "SIRT1 expression was shown to be reduced under osteogenic conditions, but notably levels were further diminished in hyperglycaemia, as calcification became more apparent." (PMID 30696833, 2019). "Taken together, AS-IV was found to mediate hyperglycaemia-triggered EMT in podocytes through SIRT1 deacetylation of NF-κB p65 subunit." (PMID 30674969, 2019). "Taken together, our data showed that AS-IV functions to activate SIRT1, which then inhibits NF-κB p65 subunit acetylation, all of which culminates in enhanced autophagy in hyperglycaemia-induced podocyte injury." (PMID 30674969, 2019). "It has been established that RSV is a potent activator of SIRT1 and the activation of SIRT1 attenuates hyperglycemia." (PMID 31565649, 2018). "Nevertheless, our findings are in line with those of a more recent study revealing increased SIRT1 expression at one day postpartum in GDM women as a consequence of their exposure to hyperglycemia during GDM." (PMID 30513672, 2018). "In tissue cultures, metformin has been shown to attenuate hyperglycemia-related endothelial senescence due to partly restoring SIRT-1 expression." (PMID 30347712, 2018). "On the other hand, a more recent study showed increased SIRT1 expression at one day postpartum in GDM women as a consequence of their exposure to hyperglycemia during GDM." (PMID 30513672, 2018). "We conclude that the increased expression of SIRT1 and PGC-1α is central to rebuffing oxidative stress caused by hyperglycemia and thus a therapeutic approach to cardiac protection." (PMID 30071860, 2018). "It has been reported that SIRT1 activation inhibits hyperglycemia-induced apoptosis by reducing OS and mitochondrial dysfunction in human endothelial cells." (PMID 29958542, 2018). "In a work on oxidative mitochondrial damage evoked by hyperglycemia the SIRT1 inhibitor has been compared to the effects of siRNA-mediated SIRT1 knock-down." (PMID 27882448, 2017). "It is possible to observe a slight, albeit insignificant, decrease in kidney SIRT1 activity after eight weeks of hyperglycemia." (PMID 28079150, 2017). "Downregulation of p66Shc expression through Sirt1 activation protects vessels from hyperglycemia-induced EC dysfunction." (PMID 28546854, 2017). "Here, we describe the role of SIRT1 causing protection against ET-1 and TGF-β1 induced endothelial damage in hyperglycaemia." (PMID 25753689, 2015). "In keeping with our earlier findings here we have shown that acting in opposing manner, p300 and SIRT1 regulate each other in hyperglycaemia." (PMID 25753689, 2015). "Resveratrol, a SIRT1 activator reduced hyperglycemia likely through activation of vagal output; however, the cellular mechanisms of action have not been determined." (PMID 24454277, 2014). "Central administration of resveratrol, a SIRT1 activator can normalize diet-induced hyperglycemia and mediate anti-diabetic actions." (PMID 24454277, 2014). "This is in stark contrast to earlier work using adenoviral-mediated hepatic SIRT1 overexpression which suggested that higher SIRT1 levels should promote hyperglycemia." (PMID 24567900, 2014). "This reciprocal activation/dynamic interaction between AMPK and SIRT1 is disrupted by hyperglycemia, which decreases AMPK expression, leading to reduced SIRT1 expression." (PMID 25346724, 2014). "Oral intubation of SA ameliorates hyperglycemia in db/db mice by reducing hepatic gluconeogenesis through the decrease of Sirt1 expression and increase in acetylated FoxO1." (PMID 25610880, 2014). "In summary, this study showed chronic hyperglycemia accelerated aging process through a novel SIRT1 and p300 regulated pathway." (PMID 23342163, 2013).
Hyperglycemia (continued). "Whereas caloric restriction enhances SIRT1 activity, hyperglycemia induces vascular cell senescence by reducing SIRT1 activity and thereby contribute to the development of diabetic vascular dysfunction." (PMID 23734259, 2013). "We found all SIRT1–7 mRNA expressions were consistently reduced with the accelerated aging process in hyperglycemia." (PMID 23342163, 2013). "We also found that hyperglycemia induces activation of caspase 3, however, only when Sirt1 expression is reduced." (PMID 21858169, 2011). "To assess the role of Sirt1 on hyperglycemia-induced podocyte apoptosis, we transduced podocytes with either a scrambled or a Sirt1-targeting shRNA." (PMID 21858169, 2011). "This study aimed to investigate the therapeutic effects of brown Yar Ko (YK) rice extract, a traditional variety from southern Thailand, on hyperglycemia-induced oxidative stress in human umbilical vein endothelial cells (HUVECs), with a focus on SIRT1 activation." (PMID 41953263, 2026). "Another study showed that hyperglycemia can be averted via DAPA through AMPK/SIRT1 pathway activation; this potentially could become the treatment target for HG-induced damage to endothelial cells." (PMID 41567643, 2025). "Hyperglycemia induces miR-195 upregulation and consequently downregulation of SIRT1 expression in the ECs of diabetic retinas, and thus SIRT1-regulated antioxidant MnSOD downregulation accelerating aging-like changes in the vascular ECs and promoting cellular senescence in the retina." (PMID 41010004, 2025). "Dulaglutide has been shown to reduce hyperglycemia-induced endothelial injury, potentially by preserving sirtuin 1 (SIRT1) levels and curbing mitochondrial fission, as well as via the downregulation of the NLR family pyrin domain containing 3 (NLRP3) inflammasome." (PMID 41008590, 2025). "NGF protects diabetic animals from hyperglycaemia-induced neuronal damage by upregulating Sirt1." (PMID 41181709, 2025). "Additionally, MEG3 overexpression results in reduced miR-34a levels and increased SIRT1 levels in retinal cells, thereby inhibiting hyperglycemia-induced apoptosis and secretion of inflammatory cytokines." (PMID 39529988, 2024). "Vascular problems result from hyperglycemia’s reduction of Sirt1 expression." (PMID 39406930, 2024). "Similarly, in retinal endothelial cells, hyperglycemia determines SIRT1 down regulation followed by a decrease of mitochondrial antioxidant enzymes levels through pathways controlled by p300 and Fork head box protein O1." (PMID 38243268, 2024). "Hyperglycemia impairs the expression of SIRT1 by depletion of cellular NAD+." (PMID 39796441, 2024). "Moreover, the IPA analysis predicted that miR-199b-5p overexpression leads to indirect activation of hyperglycemia via SIRT1 inhibition." (PMID 39125657, 2024). "Furthermore, western blot showed that these abnormal changes in mitochondrial fusion or fission protein induced by hyperglycemia were impeded by Sirt1 overexpression." (PMID 38506068, 2024). "Consequently, the increased DNA breaks caused by hyperglycemia and the impaired repair due to reduced active MRN complexes make SIRT1 activation a promising target for DNA damage repair." (PMID 37985432, 2024).
Hyperglycemia (continued). "Oxidative stress is one of the major factors contributing to wound healing difficulties in diabetic patients, and RES activates Sirtuin 1 (SIRT1) to restore hyperglycemia-induced endothelial dysfunction and angiogenic disorders, thereby promoting wound healing." (PMID 38933889, 2024). "Furthermore, a different study found high hyperglycemia results in SIRT1 downregulation and lowered SIRT1 expression." (PMID 39406930, 2024). "Another explanation for the ameliorative effect of hyperglycemia could be due to silibinin's promotion of SIRT‐1 expression, preventing autophagy, and exhibiting a reparative effect on damaged pancreatic cells." (PMID 38726421, 2024). "The aim of this study was to systematically compare the response of astrocytes within the BBB to neuroinflammation and to RSV treatment by analyzing astrocyte SIRT1 secretion in conditions corresponding to different levels of systemic glycemia (hypo-, normo-, and hyperglycemia)." (PMID 37511397, 2023). "On the other hand, AR inhibitors inhibit high glucose-induced ROS production and apoptosis in HUVECs, restore Sirtuin 1 (SIRT1) expression and phosphorylation of AMPKα1, and reduce mTOR phosphorylation, preventing hyperglycaemia-induced endothelial cell death and dysfunction." (PMID 37660030, 2023). "Inhibition of the O-GlcNAc-modified form of SIRT1 contributes to hyperglycemia by promoting the transcription of PGC-1α and FOXO1, resulting in the increased expression of phosphoenolpyruvate carboxykinase (PEPCK) and G6Pase, therefore enhancing liver gluconeogenesis." (PMID 36768465, 2023). "Metformin also prevented the hyperglycemia-induced reduction in SIRT1 protein level in these cells." (PMID 37685845, 2023). "In addition, hyperglycemia suppressed expressions of heme oxygenase 1 (HO-1) and SIRT1, which are restored by treatment with HDAC2 siRNA." (PMID 36900446, 2023). "Additionally, in the case of hyperglycemia, the protective role of SIRT-1 on the processes of proliferation and migration of endothelial cells of the cerebral microcirculation has been demonstrated in rats." (PMID 37630770, 2023). "Scientists also explained that intrauterine hyperglycemia may increase the expression of P300 and decrease the SIRT1 level in newborn neurons to increase histone H3 on lysine 14 (H3K14) acetylation." (PMID 37255932, 2023). "The treatment of the animal model with resveratrol (a SIRT1 activator) led to the elevated expression of SIRT1, which could restore autophagy activity and thus protect cells from hyperglycemia." (PMID 36601125, 2022). "Since hyperglycaemia inhibits Nrf2 by deacetylation through suppressing SIRT1, it could be possible that MA stimulates Nrf2 by activating SIRT1 directly or through its hypoglycaemic effect." (PMID 35265366, 2022). "Our previous study revealed that SIRT1 downregulation by EX-527 had a protective effect against hyperglycemia-induced kidney fibrosis, facilitated by proinflammatory cytokines, oxidative stress pathways, and cellular signaling pathways that are associated with renal fibrosis." (PMID 36139886, 2022). "Based on the results, we found that the regulation of SIRT1 might be used as a therapeutic target for hyperglycemia‐induced neurodegeneration." (PMID 36073820, 2022). "Our data provide new evidence for the relationship of melatonin and SIRT1 pathway in the context of hyperglycaemia, and melatonin as a combination therapy may be useful to combat DM-related complications, especially male reproductive system injury." (PMID 35962432, 2022). "All of this suggests that the candidate genes identified through this screen are modifying Sirt1-associated hyperglycemia directly rather than altering the degree of Sirt1 knockdown." (PMID 35435227, 2022).
Hyperglycemia (continued). "For example, metformin may increase Sirtuin 1 (SIRT1) activity and protect against hyperglycemia-induced metabolic memory resulting in endothelial dysfunction." (PMID 35455439, 2022). "Moreover, melatonin through increasing SIRT1 expression shows protective effects against hyperglycemia-induced oxidative stress and erectile dysfunction." (PMID 36465704, 2022). "Targeting SIRT1 activation can attenuate the effects of hyperglycemia and lead to decreased vascular disruption and neurodegeneration, which may have clinical potential in neurodegenerative diseases that accompany the metabolic disorder." (PMID 36073820, 2022). "Similarly, in RECs, hyperglycemia determines SIRT1 down regulation followed by a decrease of mitochondrial antioxidant enzymes levels through pathways controlled by p300 and Fork head box protein O1 (FOXO1)." (PMID 35409409, 2022). "The recovery of glucose levels rescue SIRT1 expression, suggesting that this type of intervention may rescue the progression of hyperglycemia‐mediated AD." (PMID 36073820, 2022). "The remainder of the genes had no significant or consistent impact on hyperglycemia in the model of Sirt1 loss of function." (PMID 35435227, 2022). "The mechanistic findings suggested that hyperglycemia initiated the ERS response through the negative regulation of sirtuin 1 (SIRT1), leading to the occurrence of myocardial dysfunction, and specific knockdown of MAPK10 in the heart directly reversed myocardial dysfunction induced by hyperglycemia." (PMID 35941186, 2022). "In renal tubular injury induced by hyperglycemia, SIRT1 activation could attenuate renal tubular injury through inhibiting apoptosis, which is consistent with our results that SIRT1 inhibition abolished the protective effect of crocin." (PMID 35655597, 2022). "In summary, high EVOO intake with diet decreases the likelihood of cancer and increases life expectancy because EVOO can counteract DMBA and TFA-induced damage by improving global DNA methylation pattern, while decreasing hyperglycemia, mTOR activity, and inducing SIRT1 function among other." (PMID 35215560, 2022). "Especially, hyperglycemia induced the decreased expression of cytoplasmic SIRT1 only on the 3D platform with Aß accumulation and Tau phosphorylation in neurons, which was recovered upon glucose level stabilization; however, there were no notable changes in cells cultured in 2D Transwell plates." (PMID 36073820, 2022). "Therefore, the Sirt1-PGC-1α-HO-1 axis plays a key role in protecting diabetic heart against hyperglycemia-induced OS damage." (PMID 35103095, 2022). "The modifiers could be altering the degree and efficiency of Sirt1 knockdown, so that hyperglycemia is actually correlating with the amount of Sirt1 expression that is achieved." (PMID 35435227, 2022). "In addition, the changes and regulatory role of SIRT1 by gene editing and pharmaceutic treatments were also investigated in hyperglycemia‐induced vascular‐ and neuro‐degeneration." (PMID 36073820, 2022). "Therefore, we are measuring the dominant effect of the DGRP background on the Sirt1 RNAi hyperglycemia phenotype." (PMID 35435227, 2022). "SIRT1 was verified to be the direct target of miR-34a in our previous study, and we further examined whether SIRT1 could be regulated by RSV upon hyperglycemia." (PMID 34177568, 2021). "SIRT1 activation by resveratrol has been reported to mitigate hyperglycemia-induced oxidative stress and aging in endothelial cells by recruiting mitochondrial antioxidant enzymes by recruiting DNA binding capability of FOXO1 and suppressing acetylation capacity of p300." (PMID 34071497, 2021).
Hyperglycemia (continued). "SIRT1 has also been found to inhibit hyperglycemia-provoked apoptosis in endothelial cells in vitro by inhibiting mitochondrial fission factor (Mff)-mediated mitochondrial fission, suppressing c-Jun N-terminal kinase (JNK) activation, and sustaining F-actin homeostasis." (PMID 34071497, 2021). "Moreover, Sirt1 was found to ameliorate hyperglycemia-induced oxidative stress and inflammation by intensifying the Sirt1/peroxisome proliferator-activated receptor-γ coactivator (PGC)-1α signaling pathway." (PMID 35096293, 2021). "3-(4-methanesulfonylphenoxy)-N-[1-(2-methoxy-ethoxymethyl)-1H-pyrazol-3-yl]-5-(3-methyl pyridin-2-yl)-benzamide, a glucokinase activator useful in attenuating hyperglycemia associated with T2DM in mice, can prevent cytokine-provoked β cell apoptosis via SIRT1 activation." (PMID 34071497, 2021). "Diabetic rats overexpressing the SIRT1 gene exhibited protection against oxidative stress and apoptosis in retinal tissue, which has been proposed to be mediated through the suppression of hyperglycemia-provoked p66shc activation by SIRT1." (PMID 34071497, 2021). "While SIRT1 enhances pancreatic beta cells response to hyperglycemia in insulin secretion, SIRT4 may blunt this response." (PMID 34899370, 2021). "Accordingly, regulating the expression and/or the activity of SIRT1 may be useful to manage inflammation and oxidative stress induced by hyperglycemia and hyperlipidemia in DCM." (PMID 33637069, 2021). "Support of Sirt1 activity in beta cells stressed by glucolipotoxicity may be all the more important in light of evidence that hyperglycemia can decrease Sirt1 protein expression in these cells." (PMID 35052168, 2021). "Overexpression of miR-449 inhibits the osteogenic differentiation of bone marrow mesenchymal stem cells in hyperglycemia and free fatty acid microenvironment in which SIRT1 was involved, which may play a role in the fight against diabetic osteoporosis." (PMID 34616289, 2021). "This hypothesis is supported by the observation that a 72-h exposure to metformin may reduce hyperglycemia-induced endothelial senescence and apoptosis via a SIRT1-dependent process." (PMID 33375185, 2020). "Additionally, the notable downregulation of PGC-1α and SIRT1 indicates the spermatogenic mitochondrial compromise by ROS due to T2DM induced hyperglycemia." (PMID 33375437, 2020). "Reciprocally, overexpression of SIRT1 led to hyperglycemia and impaired glucose tolerance." (PMID 31579450, 2019). "Maternal hyperglycemia decreased the mRNA level of the histone deacetylase Sirt1." (PMID 30824686, 2019). "Having confirmed an inverse correlation between hyperglycaemia-induced mineralisation and SIRT1 levels, the direct effects SIRT1 in vSMC phenotypic changes under diabetic conditions was further investigated via pharmacological manipulation to activate and inhibit SIRT1 activity." (PMID 30696833, 2019). "Activation of Sirt1 can prevent the hyperglycemia-induced vascular cell dysfunction in mice." (PMID 31406124, 2019). "It is noteworthy that we have also examined metabolic disorders in the same model and showed that offspring born to obese dams had increased body weight, hyperlipidaemia and hyperglycaemia at weaning and adolescence, which were significantly reversed by SIRT1 overexpression/activation." (PMID 30641941, 2019). "Sirt1 is an NAD+-dependent deacetylase, and we showed that the expression of Sirt1 was decreased in NP tissues, while hyperglycaemia could suppress the expression and activity of Sirt1 in NP cells." (PMID 31583043, 2019). "Similarly, liver-specific knockout mice for transcription coactivator Crtc2, a regulator of hyperglycemia and lipid metabolism, reduced miR-34a-5p and enhanced SIRT1 expressions under a fatty dietary challenge." (PMID 31500354, 2019).